CXCL10 (C-X-C motif chemokine ligand 10)
Diseases named in the same sentence as CXCL10 in open-access papers (continued):
Sharing a sentence is not in itself a finding about the gene and the disease.
sarcoma (7 papers, 2017 to 2025). A usually aggressive malignant neoplasm of the soft tissue or bone. "The remaining analytes, IL-8, IL-10, IL-12 P40, IL-24, IL-27, and CXCL10 were found in similar plasma concentrations in both patients with sarcoma and healthy subjects." (PMID 41008853, 2025). "Our collective results demonstrate that Reolysin possesses CXCL10-driven anti-angiogenic activity in sarcoma models, which can be harnessed to enhance the anticancer activity of temsirolimus and other agents that target the tumor vasculature." (PMID 29156834, 2017). "Further analysis in additional sarcoma xenograft models confirmed the significant increase in CXCL10 and increased anticancer activity of this combination." (PMID 29156834, 2017). "Beyond the eye, CXCL10 is well known for reducing angiogenesis in sarcoma, after spinal cord injury, or in the heart, suggesting that CXCL10 could be a noteworthy candidate for further research concerning vasoproliferative eye diseases." (PMID 38190125, 2024). "Furthermore, ELISA assay demonstrated that CXCL10 secretion was significantly increased in sarcoma cells exposed to Reolysin." (PMID 29156834, 2017). "However, we demonstrate that reovirus treatment strongly upregulated the anti-angiogenic chemokine CXCL10 and decreases HIF activity in sarcoma cells with differing RAS status." (PMID 29156834, 2017). "Collectively, these data provide evidence that Reolysin possesses significant anti-angiogenic activity in sarcoma models irrespective of RAS status, inhibits HIF activity, dramatically increases CXCL10 expression, and improves the efficacy of agents that disrupt angiogenesis, such as temsirolimus." (PMID 29156834, 2017).
thyroiditis (7 papers, 2009 to 2024). Inflammation of the thyroid gland. "IFN-γ-mediated CXCL10 secretion is associated to thyroiditis and is closely related to thyroid tumors." (PMID 29416784, 2018). "CXCL10 is upregulated only in PTC patients with thyroiditis and is significantly induced by IFN-γ in normal and cancer epithelial cells." (PMID 29416784, 2018). "In nMPTC, the presence of thyroiditis conditioned the increased expression of all CXCR3 ligands, but CXCL10 levels increased significantly when compared to B-CLT." (PMID 29416784, 2018). "The main possible mechanisms underlying this phenomenon are as follows: (a) IL-2 and IFN-γ may participate in the thyroid autoimmune process and affect thyroid function by blocking the PD-1/PD-L1 pathway; (b) IFN-γ and TNF-α produced by Th1 cells induce the release of CXCL10 from thyroid cells." (PMID 37051293, 2023). "Recently, the finding of high serum levels of CXCL10 but normal levels of the prototype Th2 chemokine (C-C motif) ligand 2 (CCL2) in MC + HCV patients with AT, in comparison with patients without thyroiditis, has confirmed this hypothesis." (PMID 25374602, 2014). "This hypothesis has been recently confirmed by two studies that demonstrated high serum levels of CXCL10 in MC+HCV patients and showed that CXCL10 is significantly higher in the presence of AT compared to MC+HCV patients without thyroiditis." (PMID 22611419, 2012).
vasculitis (7 papers, 2012 to 2023). "In MC+HCV patients, increased CXCL10 levels were significantly associated with the presence of active vasculitis." (PMID 31485460, 2019). "In HCV-MC patients, active vasculitis was associated with increased CXCL10 values." (PMID 31244756, 2019). "Elevated MCP-1/CCL2 and IP-10/CXCL10 likely explained the accumulation of inflammatory cells in the lung including the observed neutrophils and monocytes, and development of vasculitis that likely contributed to morbidity and mortality." (PMID 33257679, 2020). "The elevations of CCL2, CXCL10, and GM-CSF in severe disease reported here could contribute to monocyte recruitment and activation leading to this vasculitis, alongside the role of GM-CSF in the recruitment of neutrophils to the pulmonary vasculature." (PMID 33692097, 2021). "Several studies demonstrated elevated CXCL10 and TNF-α circulating levels in patients with HCV-associated cryoglobulinemia (MC+HCV) and raised CXCL10 significantly associated with the presence of active vasculitis, particularly in the presence of AT." (PMID 31485460, 2019). "For comparison the prototype Th2 chemokine (C-C motif) ligand 2 (CCL2) was not significantly different in patients with MC+HCV and active vasculitis than in MC patients, and it suggests that the Th1 CXCL10 chemokine is specifically involved in the appearance of vasculitis in these patients." (PMID 22611419, 2012). "Moreover, our studies demonstrate markedly high serum levels of CXCL10 and CXCL11 in patients with MC+HCV compared to healthy controls in particular in the presence of active vasculitis." (PMID 22611419, 2012).
viral pneumonia (7 papers, 2020 to 2025). Inflammation of the lung parenchyma that is caused by a viral infection. "Our data thus identify CXCL10 as a possible predictor of viral pneumonia outcome and response to anti-inflammatory treatment." (PMID 41307734, 2025). "In addition, our data support the use of CXCL10 as a predictor of outcomes and treatment responses in viral pneumonia." (PMID 41307734, 2025). "CXCL10 may be a marker for impaired T-cell immunity in viral pneumonia." (PMID 41307734, 2025). "Other cytokines such as IL‐8, IL‐6, interferon‐γ, CXCL10 and CXCL13 may be impacted by ozanimod, which aligns with the ability of S1P1 modulators to decrease inflammatory cytokines during viral pneumonia as seen in preclinical models." (PMID 40025871, 2025).
visceral leishmaniasis (7 papers, 2011 to 2025). A severe form of leishmaniasis characterized by irregular bouts of fever, substantial weight loss, swelling of the spleen and liver, and anemia (which may be serious). "In the context of L. infantum-induced visceral leishmaniasis, we assessed immune mediators including TNF, IL-1β, CXCL10, IL-12p70, IL-18, IL-23, and C-C motif chemokine ligand 2 (CCL2)." (PMID 40794782, 2025). "Validation of our DP cohort results revealed that CXCL10, but not CCL2, CCL5 or CXCL8 transcripts, were significantly upregulated by Leishmania infantum infection with or without clinically definite visceral leishmaniasis." (PMID 37601355, 2023).
age-related macular degeneration (6 papers, 2011 to 2024). Age-related loss of vision in the central portion of the retina (macula), secondary to retinal degeneration. "In the retina, upregulation of α and β chemokines, such as Ccl2, Cxcl1, and Cxcl10 have been detected by gene expression analyses in both wet and dry forms of age-related macular degeneration (AMD)." (PMID 25595590, 2015).
alveolitis (6 papers, 2005 to 2024). "In models of hypersensitivity pneumonitis, CXCL10 has also been shown to be necessary for granuloma formation." (PMID 24199653, 2013). "Using immunohistochemical studies of tissue sections and a flow cytometry evaluation of cells recovered from the bronchoalveolar lavage (BAL), we studied the role of CXCR3/CXCL10 interactions in the regulation of T-cell migration into the lung of patients with hypersensitivity pneumonitis." (PMID 15725351, 2005). "Reflecting the significant reduction in expression of chemokines (CCL3, CCL4, CXCL1, CXCL2, and CXCL10) in the lung, the levels of alveolitis in PKD1mKO at 24 h after the S. rectivirgula exposure was also significantly reduced compared to the levels of alveolitis in WT." (PMID 39464896, 2024). "Nasal inoculation of cotton rats with a recently isolated EV-D68 strain (VANBT/1) significantly upregulated pulmonary cytokine mRNA levels (CCL2, CCL5, CXCL1, CXCL10, IL-6, IFN-β, and IFN-γ) and provided histological evidence of peribronchiolitis and alveolitis." (PMID 34887856, 2021). "In order to analyse whether CXCL10 is expressed in vivo by lung cells of patients with hypersensitivity pneumonitis, BAL cells were stained with a anti-CXCL10 antibody." (PMID 15725351, 2005). "While WT mice show the production of IP-10/CXCL10, Mig/CXCL9, and I-TAC/CXCL11 during the development of the classic HP reaction, GKO mice have reduced or no levels of IP-10/CXCL10, Mig/CXCL9 and I-TAC/CXCL11 in the lungs and reduced T-cell alveolitis in response to SR exposure." (PMID 15725351, 2005).
atrial fibrillation (6 papers, 2018 to 2025). A disorder characterized by an electrocardiographic finding of a supraventricular arrhythmia characterized by the replacement of consistent P waves by rapid oscillations or fibrillatory waves that vary in size, shape and timing and are accompanied by an irregular ventricular response. "CXCL-10-overexpression promotes structural remodeling and consequently atrial fibrillation, therefore increased levels of MIAT in circulating EV might indicate a disease progression in AF patients." (PMID 39314768, 2024). "Elevated levels of CXCL8, CCL11, CCL2, CXCL10, IL-1β, IL-6, TNF-α, IFN-γ, IL-17, IL-1Ra, IL-4, IL-9, FGF-basic, PDGF, G-CSF, and GM-CSF were observed in the Atrial fibrillation patient, in contrast to uninfected controls." (PMID 29370812, 2018).
cardiomyopathy (6 papers, 2016 to 2024). A disease of the heart muscle or myocardium proper. "C-X-C chemokine ligand 10 (CXCL10) is involved in myopathy and cardiomyopathy development and is associated with a more severe SSc prognosis." (PMID 33809279, 2021). "In human cardiomyocytes cultures, empagliflozin significantly reduced the release of the interferon (IFN)γ-induced 10 kDa protein (IP-10/CXCL10), a chemoattractant associated with inflammation and development of cardiomyopathy." (PMID 36552708, 2022). "Furthermore, sildenafil decreased CXCL10 blood level higher than 930 pg/ml (cut-off value) in diabetic subjects at cardiomyopathy onset." (PMID 27165639, 2016). "In light of those preliminary evidences, we speculate that sildenafil could be a new therapeutic option to control cardiomyopathy onset/progression in diabetic subjects while CXCL10 could represent a novel tool to identify patients to treat since early stages." (PMID 27165639, 2016). "Interestingly, CXCL10 and CXCL8 significantly increased in sera of diabetic subjects at the onset of cardiomyopathy and are targeted by sildenafil." (PMID 39355618, 2024). "We analyzed: CXCL10 gene and protein in human cardiac, endothelial, and immune cells challenged by pro-inflammatory stimuli with and without sildenafil; serum CXCL10 in diabetic subjects at cardiomyopathy onset, before and after 3 months of treatment with sildenafil vs. placebo." (PMID 27165639, 2016).
chorioamnionitis (6 papers, 2012 to 2025). A morphologic finding indicating inflammation of the fetal sac membranes. "As an example, in the chorioamnionitis, placental inflammatory lesions parallel an increase in CXCL10, CXCL11 and CXCL12 concentrations in maternal plasma." (PMID 24849800, 2014).
Chronic colitis (6 papers, 2009 to 2022). A chronic inflammatory disease of the large intestine (colon, cecum and rectum). "Studies in animal models have also shown that the leukocyte-derived CXCL10 is associated with chronic colitis, and that the blockade of CXCL10 with anti-CXCL10 antibody may abrogate the inflammatory response." (PMID 19421322, 2009). "We have also shown that antibody-mediated neutralization of the CXCR3 ligand CXCL10 inhibits chronic colitis in IL-10-/- mice." (PMID 21858153, 2011). "Most strikingly was the reduction of Tnfα, Cxcl10, and other proinflammatory and profibrogenic genes in livers of IL-37tg mice during chronic colitis suggesting that IL-37 modulates fibrosis both by inhibiting inflammation and downregulating fibrosis-inducing pathways." (PMID 33746950, 2021).
demyelination (6 papers, 2007 to 2022). "This CXCL10-induced microglial movement has been linked to efficient myelin debris clearance in a cuprizone-induced demyelination model." (PMID 35892669, 2022). "M. leprae induces neural demyelination by stimulating the production of matrix metalloproteinases (MMPs), C-X-C motif chemokine ligand 10 (CXCL10) and C-C motif chemokine 2 (CCL2), which attract macrophages." (PMID 36326715, 2022). "Vazirinejad and coworkers and others have found elevated circulating (serum) or CSF content of CXCL10 and have proposed that CXCL10 contributes importantly to inflammatory demyelination that is an essential component of MS." (PMID 27493972, 2016). "The analysis of chemotactic factors in cuprizone induced demyelination revealed an increased expression of CCL-2, CXCL-10, and HGF in the corpus callosum suggesting a potential source of the CNS to attract MSC into the lesion." (PMID 23922802, 2013). "Immunization with MOG peptide, i.e., induction of EAE during CPZ-induced demyelination resulted in microglia activation in contrast to classic EAE, and also potentiated gene expression of CXCL10, CCL2, and CCL3 in the corpus callosum beside additional brain areas." (PMID 32582192, 2020).
diabetic cardiomyopathy (6 papers, 2016 to 2022). Diabetic cardiomyopathy is a disorder of the heart muscle in people with diabetes. "We aimed to evaluate the effect of sildenafil on CXCL10 in inflammatory conditions associated with diabetic cardiomyopathy." (PMID 27165639, 2016). "In light of those evidences the authors speculated that sildenafil could be a new tool to control CXCL10-associated inflammation in diabetic cardiomyopathy." (PMID 28210757, 2017). "To verify whether PDE5 inhibition might affect in vivo Th1-associated conditions, we measured CXCL10 level in blood of subjects with diabetic cardiomyopathy before and after sildenafil intake." (PMID 27165639, 2016). "In conclusion, sildenafil could be a pharmacologic tool to control CXCL10-associated inflammation in diabetic cardiomyopathy." (PMID 27165639, 2016). "Accordingly, we have previously reported in vivo and in vitro on the sildenafil-induced inhibition of CXCL10 in diabetic cardiomyopathy, an inflammation-driven co-morbid condition." (PMID 33809279, 2021). "The group observed that sildenafil significantly decreased CXCL10 in human cardiomyocytes and decreased circulating CXCL10 in patients with diabetic cardiomyopathy." (PMID 28210757, 2017). "Interestingly, the phosphodiesterase type 5 inhibitor (PDE5i) sildenafil reduces CXCL10 sera levels of patients with diabetic cardiomyopathy and in cardiomyocytes." (PMID 33809279, 2021). "Sildenafil was also introduced as another potential therapeutic agent that coulddecrease CXCL10 production inboth protein and mRNA levels in human cardiac myocytes and further attenuate the circulating CXCL10 in diabetic cardiomyopathy patients." (PMID 34835155, 2021). "Furthermore, we aimed to investigate circulating level of CXCL10 in subjects with diabetic cardiomyopathy, a Th1-driven comorbid condition, before and after 3 months sildenafil intake vs. placebo." (PMID 27165639, 2016). "Another potential therapeutic approach is the phosphodiesterase type 5 inhibitor sildenafil, which was recently reported to decrease CXCL10 gene expression and protein secretion in human cardiac myocytes and decrease circulating CXCL10 in subjects with diabetic cardiomyopathy." (PMID 27795961, 2016). "We have previously reported on the pivotal role of the interferon (IFN)γ-induced 10-kDa protein (IP-10/CXCL10), a chemokine engaged in early stages of T helper 1 (Th1)-driven cardiac inflammation and disease development, including diabetic cardiomyopathy (DCM)." (PMID 35712355, 2022).
Ewing sarcoma (6 papers, 2021 to 2025). A small round cell tumor that lacks morphologic, immunohistochemical, and electron microscopic evidence of neuroectodermal differentiation. "Patients with Ewing sarcoma showing high levels of CXCL10 had slightly better OS (p = 0.049), but IL-24 and CXCL5 levels had no prognostic significance." (PMID 41008853, 2025). "Upon activation, NK cells secrete IFNγ, which feeds back on USP6-expressing Ewing sarcoma cells to synergistically induce CXCL9/CXCL10." (PMID 37615015, 2023). "Synergistic induction of CXCL9/CXCL10 was completely ablated by IFNGR1 depletion, and partly inhibited by IFNAR1 depletion, indicating that Ewing sarcoma–intrinsic signaling through both pathways contributes to this feedforward loop." (PMID 37615015, 2023). "Intracellular flow cytometry confirmed that the USP6/Ewing sarcoma cells, and not the NK-92, were the predominant source of CXCL10." (PMID 37615015, 2023). "Moreover, many pediatric neuroblastoma, Ewing sarcoma (ES), osteosarcoma, and ALL, show altered expression of circulating cytokines/chemokines such as CCL2, CXCL4, CXCL6, CXCL10, and CXCL12." (PMID 38927907, 2024). "Furthermore, USP6-expressing Ewing sarcoma and NK cells participate in a paracrine immunostimulatory feedforward loop, wherein IFNγ secreted by activated NK cells feeds back on USP6/Ewing sarcoma cells to induce synergistic expression of chemokines CXCL9 and CXCL10." (PMID 37615015, 2023).
fibrosarcoma (6 papers, 2014 to 2025). A malignant mesenchymal fibroblastic neoplasm affecting the soft tissue and bone. "Mice with fibrosarcoma treated with CXCL10 combined with hypothermia presented reduced tumor burden and MVD, whereas the MMP2-inhibitor TIMP2, have been recently described as important prognostic factors in acute lymphoblastic leukemia." (PMID 26099922, 2015). "Based on the observation that CXCR3+ T cells are significantly enriched in MCA-induced tumours, we postulated that the CXCR3-binding chemokines (such as CXCL10) were likely candidates for recruitment of T cells to the fibrosarcomas." (PMID 25495686, 2015). "In addition, Majumder and co-workers found evidence that IFN γ and TNF α act in synergy via p48 complexes with STAT-1α binding to this same ISRE site in the CXCL10 promoter of human fibrosarcoma lines." (PMID 25033426, 2014). "For example, a preclinical study found pretreatment with trabectedin improved the response to anti–PD-1 in a murine model of fibrosarcoma and led to upregulation of CD8, GZMB, PRF1, and CXCL10 mRNA expression in trabectedin-treated tumors." (PMID 39777457, 2025).
glaucoma (6 papers, 2015 to 2024). Increased pressure in the eyeball due to obstruction of the outflow of aqueous humor. "We found the mRNA expression of cGAS-STING signaling downstream genes Il6, Ifnb, and Cxcl10 were increased in glaucoma as compared to the sham group." (PMID 38848144, 2024). "Moreover, ELISA analysis showed the level of IL-6, IFN-β, and CXCL10 were also elevated in glaucoma as compared to the sham group, suggesting an inflammatory response in glaucoma." (PMID 38848144, 2024). "So far, Cxcl10, Myc, Timp1, Serpina3n, and Ednrb have been reported to be upregulated in retinas after light damage or other injury/diseases models such as retinal detachment, glaucoma, or retinal ischemia-reperfusion." (PMID 33614628, 2020).